CSTF2T (cleavage stimulation factor subunit 2 tau variant)
Description:
May play a significant role in AAUAAA-independent mRNA polyadenylation in germ cells. Directly involved in the binding to pre-mRNAs (By similarity).
Synonyms: KIAA0689; DKFZp434C1013; CstF-64T; tauCstF-64
Tractability: PROTAC: ubiquitination databases record sites on it; its protein half-life has been measured.
Gene: Protein-coding gene on chromosome 10 (51,695,486 to 51,699,595, reverse strand). Ensembl gene ENSG00000177613.
Subcellular location: Nucleus
Subcellular location (Human Protein Atlas): Nucleoplasm; Basal body; Vesicles
Pathways (Reactome):
Metabolism of RNA: Processing of Intronless Pre-mRNAs; mRNA 3'-end processing; mRNA Polyadenylation
Disease: Dengue Virus-Host Interactions
Gene expression (Transcription): RNA Polymerase II Transcription Termination
Gene Ontology:
Molecular function: protein binding; RNA binding; nucleic acid binding
Biological process: mRNA 3'-end processing
Cellular component: mRNA cleavage and polyadenylation specificity factor complex; nucleoplasm; nucleus
Genetic constraint (gnomAD): Loss-of-function variants: 18 observed, 41.24 expected, observed/expected ratio (o/e) 0.44, 90% interval 0.3 to 0.65. The upper end of that interval is the gene's LOEUF score, 0.65, which puts it in group 2 of 6, group 1 being the genes least tolerant of losing a copy. Missense variants: 681 observed, 839.33 expected, observed/expected ratio (o/e) 0.81, 90% interval 0.76 to 0.86. Synonymous variants: 291 observed, 295.73 expected, observed/expected ratio (o/e) 0.98, 90% interval 0.89 to 1.08.
Homologues: Orthologues: macaque CSTF2T (98% identical), pig CSTF2T (94% identical), guinea pig CSTF2T (91% identical), mouse Cstf2t (91% identical), rat Cstf2t (91% identical), dog CSTF2T (85% identical), Drosophila melanogaster CstF64 (36% identical), Caenorhabditis elegans cpf-2 (26% identical), Caenorhabditis elegans R06C1.4 (7% identical). Paralogues in human: CSTF2 (70% identical), U2AF2 (13% identical), RBMX2 (13% identical), ZCRB1 (9% identical), UHMK1 (7% identical).
Diseases named in the same sentence as CSTF2T in open-access papers:
CSTF2T is named in the same sentence as 10 diseases in open-access papers, as found by Europe PMC text mining. Sharing a sentence is not in itself a finding about the gene and the disease. The quoted sentences say what the papers report.
male infertility (3 papers, 2016 to 2022). The inability of the male to effect fertilization of an ovum after a specified period of unprotected intercourse. "CSTF2T plays a potential role in infertility as a mutation in this gene caused male infertility in humans." (PMID 36712875, 2022). "Previously knockout of such types of retrogenes, including Cetn1, Cstf2t, Pgk2 and Rpl10l, always resulted in spermatogenic abnormalities and male infertility." (PMID 34249105, 2021). "Targeted disruption of the testis-expressed polyadenylation gene Cstf2t resulted in severe male infertility, demonstrating a critical necessity for polyadenylation and mRNA processing in spermatogenesis." (PMID 27812195, 2016).
Anxiety (1 paper, 2016). Intense feelings of nervousness, tension, or panic often arise in response to interpersonal stresses. "Both male and female mice deficient in Crem display decreased anxiety, in a manner similar to Cstf2t-deficient mice." (PMID 27812195, 2016). "We speculate, therefore, that Cstf2t participates in a balance of increasing anxiety to reduce risk-taking activities, while reducing aspects of learning and memory that enable such activities." (PMID 27812195, 2016). "Cstf2t-/- males and females showed less thigmotaxis, which is often an indication of anxiety, than wild types." (PMID 27812195, 2016). "This suggests that male Cstf2t-/- mice were able to acclimate to the test better than their wild type brothers, and displayed less apparent anxiety while doing so." (PMID 27812195, 2016). "Perhaps there are specific mechanisms enabled by Cstf2t in the amygdala that enhance functional anxiety, but that suppress learning and memory in the hippocampus." (PMID 27812195, 2016). "It seems incongruous that disruption of a gene for mRNA 3′ end processing such as Cstf2t would result in an increase in learning and memory while reducing anxiety." (PMID 27812195, 2016). "These suggest mechanisms by which Cstf2t could affect learning, memory, and anxiety through alternative polyadenylation and splicing, which would increase plasticity and learning." (PMID 27812195, 2016). "Ignoring, for the moment, that Cstf2t-/- males are infertile, we can only speculate that pathways of anxiety have an unknown benefit in males, possibly in avoidance of dangerous situations." (PMID 27812195, 2016). "Interestingly, male Cstf2t-/- mice displayed less thigmotactic behavior than did wild type mice, suggesting that Cstf2t may play a role in anxiety in males." (PMID 27812195, 2016). "Cstf2t-/- males also required reduced times to finish the radial arm maze task and increased activity in the open field test, behaviors that could be explained by decreased anxiety." (PMID 27812195, 2016). "We also saw decreased thigmotactic swimming in Cstf2t-/- male mice, suggestive of decreased anxiety in the absence of τCstF-64." (PMID 27812195, 2016). "However, the current work suggests the opposite model: Cstf2t acts to suppress—though not eliminate—spatial learning and memory while enhancing anxiety." (PMID 27812195, 2016).
atherosclerosis (1 paper, 2023). A disease characterized by the build-up of fatty material and calcium deposition in the arterial wall resulting in partial or complete occlusion of the arterial lumen. "Strengths of this study focused on that we found that CAD GWAS risk variants at the CSTF2T locus were closely associated with increased CSTF2T expression in whole blood tissue, suggesting that CSTF2T may promote atherosclerosis, which may be a future direction for the treatment of atherosclerosis." (PMID 37465452, 2023).
tumor (2 papers, 2024 to 2025). "Lastly, CSTF2T was linked to chromatin remodeling and TGF‐beta signaling pathways, suggesting its role in regulating gene expression and shaping the tumor microenvironment." (PMID 40817807, 2025). "In our study, 10q11.23 (PRKG1), 10q22.1 (CSTF2T), 10p12.33 (MRC1), and 10p12.1 (STAM) occurred in 37.5% of ChRCC and not in RO, indicating the potential of the two cytobands in differentiating the two tumours." (PMID 39684226, 2024).
cancer (1 paper, 2024). A tumor composed of atypical neoplastic, often pleomorphic cells that invade other tissues. "In the first enriched pathway, surveillance pathway, five genes (HBS1L, DAZAP1, RBM8A, CSTF3, and CSTF2T) overlap, all of which have been previously implicated in cancer progression." (PMID 38305998, 2024).
CSTF2T also shares sentences with these, for which no sentence is quoted: infertile (2 papers); Anosmia (1); colorectal adenocarcinoma (1); COVID-19 (1); myopathy (1).